TRAV17 (T cell receptor alpha variable 17)
Description:
V region of the variable domain of T cell receptor (TR) alpha chain that participates in the antigen recognition. Alpha-beta T cell receptors are antigen specific receptors which are essential to the immune response and are present on the cell surface of T lymphocytes. Recognize peptide-major histocompatibility (MH) (pMH) complexes that are displayed by antigen presenting cells (APC), a prerequisite for efficient T cell adaptive immunity against pathogens. Binding of alpha-beta TR to pMH complex initiates TR-CD3 clustering on the cell surface and intracellular activation of LCK that phosphorylates the ITAM motifs of CD3G, CD3D, CD3E and CD247 enabling the recruitment of ZAP70. In turn ZAP70 phosphorylates LAT, which recruits numerous signaling molecules to form the LAT signalosome. The LAT signalosome propagates signal branching to three major signaling pathways, the calcium, the mitogen-activated protein kinase (MAPK) kinase and the nuclear factor NF-kappa-B (NF-kB) pathways, leading to the mobilization of transcription factors that are critical for gene expression and essential for T cell growth and differentiation. The T cell repertoire is generated in the thymus, by V-(D)-J rearrangement. This repertoire is then shaped by intrathymic selection events to generate a peripheral T cell pool of self-MH restricted, non-autoaggressive T cells. Post-thymic interaction of alpha-beta TR with the pMH complexes shapes TR structural and functional avidity.
Synonyms: TCRAV17S1; TCRAV3S1
Gene: T-cell receptor variable (V) gene on chromosome 14 (21,997,539 to 21,998,168, forward strand). Ensembl gene ENSG00000211797.
Subcellular location: Cell membrane
Gene Ontology:
Biological process: response to bacterium
Cellular component: plasma membrane
Homologues: Orthologues: chimpanzee TRAV17 (81% identical), macaque TRAV17 (77% identical), mouse Trav8d-1 (70% identical), mouse Trav8-1 (69% identical), mouse Trav8n-2 (69% identical), mouse Trav8d-2 (67% identical), rabbit TRAV17 (66% identical). Paralogues in human: TRAV6 (54% identical), TRAV21 (51% identical), TRAV10 (46% identical), TRAV7 (46% identical), TRAV39 (44% identical), TRAV27 (43% identical), TRAV20 (42% identical), TRAV25 (39% identical), TRAV34 (39% identical), TRAV13-1 (38% identical), TRAV5 (38% identical), TRAV13-2 (36% identical), and 11 more.
Diseases named in the same sentence as TRAV17 in open-access papers:
TRAV17 is named in the same sentence as 3 diseases in open-access papers, as found by Europe PMC text mining. Sharing a sentence is not in itself a finding about the gene and the disease. The quoted sentences say what the papers report.
COVID-19 (1 paper, 2021). A disease caused by infection with severe acute respiratory syndrome coronavirus 2. "In the CD4+ T cells of COVID-19 patients at the two-week convalescent stage, 37 unique pairs of VJ rearrangement of TRA were found, such as TRAV8-4/TRAJ54 and TRAV17/TRAJ54, and 23 specific pairs of TRB VDJ patterns were also found in CD4+ T cells." (PMID 35011632, 2021).
primary biliary cholangitis (1 paper, 2025). Primary biliary cholangitis (PBC) is a chronic and slowly progressive cholestatic liver disease of autoimmune etiology characterized by injury of the intrahepatic bile ducts that may eventually lead to liver failure. "For the α chain, Trav10 [S26], Trav16n [S20,26], Trav17 [S27], Trav5‐4 [S26], Traj42 [S20,26] and Traj53 [S26] were associated with Type I diabetes, whereas Trav12‐2 [S28] was associated with primary biliary cholangitis." (PMID 40665793, 2025).
TRAV17 also shares sentences with these, for which no sentence is quoted: Type I diabetes (1 paper).